APOE (apolipoprotein E)
Diseases named in the same sentence as APOE in open-access papers (continued):
Sharing a sentence is not in itself a finding about the gene and the disease.
dementia (continued). "The results from this study render support to the hypothesis that white matter microstructure partly mediate the effect of APOE on PS in very old persons without dementia." (PMID 26252210, 2015). "The difference in the magnitude of the OR for the AD-GRS with and without APOE in NHB predicting dementia probability (1.33–1.72) supports the hypothesis that APOE is not as strong a predictor of dementia in NHB as in NHW." (PMID 25328845, 2014). "Thus, the primary aim of this study was to assess the influence of variations in the TOMM40 gene on HC volume and EM in old adults (>60) without dementia, taking into account APOE genotype status." (PMID 23734114, 2013). "Although there was some evidence for a protective effect of E3 alleles in CJD patients, this study does not support the hypothesis of a systematic role of ApoE genotypes in BBB function in individuals with a diagnosis of dementia." (PMID 24386372, 2013). "More recently, it was shown that E2 replacement may be beneficial in ApoE ε4 carriers although it did not significantly prevent from dementia for the whole sample." (PMID 22216027, 2011). "One population based study investigated the effect of DHA and EPA on cognitive performance of 302 elderly people > 65 years without dementia and detected no treatment effects over 26 weeks, although it did report improvements in attention in apoE-4 carriers and males." (PMID 22254013, 2010). "However, APOE ε4 did modify the relation between stroke and dementia as those with stroke who were APOE ε4 negative had two times higher odds of dementia, while those with stroke who were APOE ε4 positive had 15 times higher odds of dementia." (PMID 20576093, 2010). "It is important to understand to what extent lifestyle factors contribute to brain structural differences in older people without dementia, between carriers and non-carriers of APOE e4, which might aid the development of corresponding interventions for better brain health." (PMID 41140810, 2025). "The results suggest that the negative effect of APOE e4 on cognitive functioning becomes greater with age; this urges more work to understand the mechanisms by which e4 status renders the older person’s brain increasingly vulnerable to cognitive decline and dementia." (PMID 40386430, 2025). "Contribution of peripheral apoE was also confirmed by a human cohort study showing that high apoE levels in HDL that lacked apoC3, which is an apolipoprotein secreted by liver and small intestine, was associated with better cognitive function and lower dementia risk." (PMID 40275327, 2025). "Therefore, our findings may not generalize to later stages of dementia, where relationships between APOE ɛ4 status and brain structure may be more complex." (PMID 38384997, 2024). "Moreover, it is possible to debate whether AD patients carry an APOE-ε4 allele, without performing the genetic test for patients with APOE-ε4 status, which depicted hyperperfusion condition along with early dementia onset." (PMID 38497046, 2024). "Also, we could not adjust for carriage of the ε4 allele of the apolipoprotein E gene (APOE), the most common genetic risk factor for AD, and we could not distinguish between dementia subtypes." (PMID 39234294, 2024). "Additionally, it is relevant to highlight that up to date, it is still unclear how the total concentration of apoE nor its isoforms could be related to the Aβ, p-tau status, the degree of dementia, or affect other biological parameters." (PMID 36153580, 2022). "Therefore, we could not analyze the role of APOE E4 in the association between the H1RA and risk of dementia." (PMID 35370616, 2022). "There is evidence that the effects of APOE e4 variation on brain functioning increase across the lifespan, i.e. differences between e4 carriers vs. non-carriers in terms of cognitive ability become more pronounced with older age regardless of outright dementia." (PMID 30903549, 2020).
dementia (continued). "Although no direct interactions between PBV and APOE were observed, both the protective APOE ε2ε3 genotype and high (protective) levels of PBV were associated with higher HDL-R and higher HDL-R was independently associated with higher cognition and a lower odds of dementia." (PMID 31022959, 2019). "The APOE ε4 allele seems to increase the risk for dementia in the presence of cardiovascular pathology, and a lower prevalence of the APOE4 allele could reduce the negative effect of vascular disorders on dementia incidence." (PMID 31097030, 2019). "However, few studies address these issues in human brain from those who either age without dementia and overt neuropathology, or succumb to Alzheimer's; especially as such propensity may be influenced by APOE genotype." (PMID 25859183, 2015). "Significantly associated proteins at a false discovery rate (FDR) < 0.05 in both models 1 and 2 were CGREF1, MET, ALDH2, NECTIN2, APOC1, APOE and FOSB for HFRS, and CDK and POF1B for HFRS without dementia." (PMID 40764432, 2025). "Data from 1954 participants were included from the PREVENT-Dementia and ALFA (ALzheimer and FAmilies) studies (mean age = 57, 1197 non-carriers and 757 apolipoprotein E ɛ4 carriers)." (PMID 38384997, 2024). "This analysis, though, did not account for DR duration or APOE genotype and relied on ICD codes for dementia diagnoses, rather than expert consensus or research criteria." (PMID 38699385, 2024). "Amongst the 13,007 participants where genetic data was available, the HDL-C-PRS (not including APOE) was added to the fully adjusted model to determine whether genetic influences on HDL-C levels could explain the association observed between elevated HDL-C and dementia risk." (PMID 38456089, 2024). "However, longitudinal analyses performed with the community-based cohort showed that the combination of SCC with APOE ε4 and GFAP could have the potential to contribute to the differentiation between future risk of all-cause dementia and risk of depression in the absence of dementia." (PMID 37951931, 2023). "However, evidence of interactive effects of APOE genotype with diet is suggested by findings that younger APOE ε4 carriers in preclinical stages may benefit mostly from lifestyle interventions, whereas older APOE ε4 noncarriers with dementia may show the most pronounced effects." (PMID 36841786, 2023). "The results for plasma ApoA1 were significant for both APOE ε4 carriers and non-carriers in the MCI and dementia groups for at least one of the three cognitive measures tested (MMSE, CDR-SB, and LM)." (PMID 36927447, 2023). "Using brains from the Religious Order Study (ROS), this study compared measures of brain eicosanoid lipidome in older persons with AD dementia to age-matched controls with no cognitive impairment (NCI), stratified by APOE genotype." (PMID 36217192, 2022). "Therefore, the lack of an association between APOE and non-amnestic cognitive domain scores in our sample may stem from selecting only participants without dementia, as more robust APOE effects on neurodegeneration and cognition have been reported in participants with dementia." (PMID 33521872, 2021). "Therefore, an established model incorporating aging, ApoE ε4 genotype, olfactory decline, an increased plasma Aβ1-42/Aβ1-40, and an increased platelet GSK-3β activity has a great potential for predicting who may develop dementia (including AD) in T2DM patients." (PMID 34746146, 2021). "However, after adjusting for age, sex, APOE ε4 carriage, and baseline MoCA score, minor allele carrier status of rs68006382 was associated with accelerated conversion to MCI (HR = 1.973, 95% CI = 1.246–3.123, p = 0.004), but not dementia (HR = 1.512, 95% CI = 0.753–3.034, p = 0.245)." (PMID 35356146, 2021). "Evidence suggests a link between APOE genotype and docosahexaenoic acid (DHA); however, clinical studies with current DHA supplements have produced negative results in dementia." (PMID 34276296, 2021).
dementia (continued). "Although the level of [11C]PIB retention differed somewhat between centres (p = 0.003), it was neither related to dementia severity, which was mild and very similar across all centres (MMSE 24 ± 3), nor to ApoE ε4 genotype or patient age." (PMID 22961445, 2013). "CSF and serum TTR values were neither significantly associated with clinical parameters (age at onset of parkinsonism, duration of parkinsonism, Hoehn&Yahr stage, age at onset of dementia, duration of dementia, MMSE score), nor with ApoE status." (PMID 23133543, 2012). "However, no substantial correlation was found between APOE genotypes affecting the NOS3 genotype in AD and dementia." (PMID 38790243, 2024). "However, inclusion of APOE ε4status in CogDrisk and ANU-ADRI did not change the estimative value for dementia in any of the cohorts under investigation (results not shown)." (PMID 37647064, 2023). "However, the possible influence of the APOE-Ɛ4 on the relation between comorbid NPS and conversion to dementia in MCI patients has never been explored." (PMID 33742011, 2021). "Furthermore, an independent study using the UK Biobank cohort recently suggested that APOE ε4ε4 genotype increases the risks of severe SARS-CoV-2 infection, independent of preexisting dementia, cardiovascular disease, and type-2 diabetes." (PMID 34945790, 2021). "In addition, in individuals without dementia, IGF-I receptor stimulating activity was lower in homozygote carriers of ApoE-ε4 than in people with other ApoE genotypes." (PMID 30809143, 2019). "We previously performed a deep pathological phenotyping of a large cohort of PD patients (n=140), who died with or without dementia and included systematic evaluation of SYN, Tau NFTS, Aβ plaque, TDP-43, CVD and HpScl, as well as genotyping for Apolipoprotein E (APOE) and MAPT tau haplotype." (PMID 30473927, 2018). "We hypothesized that there would be a similar additive effect of the AD-GRS on dementia probability and memory score in NHW and NHB, regardless of the inclusion of the APOE gene or age at assessment." (PMID 25328845, 2014). "Thus, further research is required in normal old adults before we can tease out the influence of genetic variation in APOE and TOMM40 on HC volume and EM memory, irrespective of dementia." (PMID 23734114, 2013). "Given that plasma biomarkers were associated with cognitive decline and disease progression in participants without dementia, we decided to assess whether they could help improve the DAT diagnosis that could be achieved at the primary care level using only age, sex, and APOE genotype." (PMID 39253733, 2024). "However, NPS might not be considered as sole marker of cognitive decline or dementia, given that in our study, CAA subgroups (ICH, cognitive decline, and AD pathology) did not affect NPS prevalence and our models were controlled for age, AD pathology and APOE status." (PMID 39232823, 2024).
cognitive decline (1,053 papers, 2006 to 2026). "CAIDE, CHAP and WHICAP showed evidence of ApoE ε4 status potentially mediating SFAs and AD risk or cognitive decline." (PMID 41601895, 2026). "Only berry consumption and berry consumption>100 g/d were associated with cognitive decline in the APOE ε4 carriers (eTable 4)." (PMID 39890535, 2025). "Overall, the TOMM40 rs2075650 variant appears to play a role in cognitive decline progression, but its exact mechanism and possible connection with APOE remain subjects of ongoing research." (PMID 41465142, 2025). "While the mechanisms behind APOE ε2's protective effects are not fully understood, its role in reducing AD risk and slowing cognitive decline is thought to be linked primarily to its impact on cortical Aβ deposition." (PMID 40613482, 2025). "It is important to discover what it is about possessing one or more APOE e4 alleles that results in steeper cognitive decline." (PMID 40386430, 2025). "APOE 4 allele is the most important genetic risk factor associated with cognitive decline and AD thus studies focusing on women and APOE 4 status are critical." (PMID 41065881, 2025). "For instance, PRS models for AD that incorporate APOE ε4 alongside other risk loci have demonstrated the ability to stratify patients based on their likelihood of rapid cognitive decline." (PMID 40004464, 2025). "This is supported by direct evidence correlating decreasing CSF apoE levels with cognitive decline and risk for AD." (PMID 40275327, 2025). "The influence of the APOE ε4 allele, a major genetic risk factor for AD, also appears more pronounced in women, particularly regarding cognitive decline and associations with tau pathology." (PMID 41446640, 2025). "Adjusting for APOE 4, a well-established genetic risk factor for cognitive decline, rendered the association between PBF consumption and cognition non-significant, suggesting that initial models likely suffered from residual confounding." (PMID 41065881, 2025). "Contributions of Aβ burden and APOE genotype on cognitive performance were also risk factors for cognitive decline in participants with LLD." (PMID 40672452, 2025). "The formation of C1q-ApoE complexes has been associated with cognitive decline, and suppression of complement protein C5 has been shown to reduce inflammation." (PMID 39944166, 2025). "Collectively, these results demonstrate a role of apoE in preserving BBB integrity in pericytes and either loss of apoE or expression of the apoE4 isoform induces BBB breakdown that precedes cognitive decline in AD." (PMID 40275327, 2025). "This study aims to investigate the relationships between relative leukocyte telomere length, cardiovascular risk factors, body composition, and APOE polymorphisms in cognitive decline contexts among older adults." (PMID 40303469, 2025). "Recent findings have expanded the sex differences in APOE-ε2 and their role in AD risk and cognitive decline." (PMID 40067298, 2025). "This heightened vulnerability to APOE ε4 among women is supported by epidemiological evidence showing that women with at least one copy of APOE ε4 exhibit greater risk and faster cognitive decline relative to men." (PMID 41446640, 2025). "It is well established that demographic variables, such as greater age, fewer years of educational attainment, and APOE-ε4 genotype, are risk factors for cognitive decline." (PMID 40993981, 2025). "On the other hand, in CU participants who had completed the questionnaires, those also willing to undergo amyloid-PET examination were often diagnosed subjective cognitive decline with abnormal plasma biomarkers and/or carrying APOE ε4 alleles." (PMID 39890535, 2025). "Recent studies have suggested that APOE ε4 is linked to faster cognitive decline, with cognitive trajectories correlating with motor deterioration." (PMID 41180817, 2025).
cognitive decline (continued). "These co-pathologies not only correlate with cognitive decline but also contribute to a reduction in diagnostic accuracy, especially in very late-onset cases, and are further modulated by APOE-ε4 status." (PMID 40968282, 2025). "The SNPs of rs429358 in APOE genotype C and rs7412 in APOE genotype T are risk factors for cognitive decline." (PMID 40672452, 2025). "Both WMH volumes and cognitive decline share known risk factors including age, lower education, female sex, APOE-ɛ4 allele, kidney health and cardiovascular risk factors." (PMID 40966613, 2025). "The other study targeting the inter-relations was a longitudinal study investigating the association of hippocampal volume loss, APOE genotype, cognitive decline, and Aβ status in CN participants." (PMID 40167963, 2025). "FAM83E, associated with global cognitive decline in APOE 3/3 individuals, is a tumor suppressor gene linked to posterior cortical atrophy (PCA), which causes visuospatial and language dysfunction due to parietal and occipital cortex degeneration." (PMID 40725187, 2025). "A key genetic risk factor for cognitive decline and Ad is the apolipoprotein E4 (APOE4) allele, which has been associated with weakening of the blood–brain barrier." (PMID 39876877, 2025). "In contrast, other studies have not demonstrated any significant association between a PRS specific for AD and cognitive decline, or the observed association was driven by the influence of the APOE genotype." (PMID 39940679, 2025). "APOC1 influences AD development through its role in cholesterol metabolism, with the APOC1 H2 allele potentially acting synergistically with APOE to increase the risk of cognitive decline." (PMID 40557283, 2025). "Our findings emphasize the substantial role of cerebrovascular pathology in the development of cognitive decline in middle-aged to older (mean age 65 years) carriers of the APOE ε4 allele." (PMID 40344552, 2025). "In the models for cognitive decline, significantly associated variables included the number of APOE ε4 risk alleles (fully adjusted model, 1 versus 0, p = 0.012; 2 versus 0, p < 0.001), and primary versus higher education in models 2-4 (model 4, p = 0.030)." (PMID 41384827, 2025). "APOE was identified as the top gene associated with accelerated cognitive decline and, to a lesser extend, with lower levels of cognitive function." (PMID 40374629, 2025). "Overall, our findings suggest that even in clinically unimpaired individuals, short sleep duration and the APOE ɛ4 carriers are associated with altered LC-FC patterns, potentially predisposing them to cognitive decline." (PMID 40994826, 2025). "Apolipoprotein E4 (APOE4) genotype and nitric oxide (NO) deficiency are risk factors for age-associated cognitive decline." (PMID 39876877, 2025). "Regarding the covariates, older age and APOE*4 allele were strongly associated with lower baseline cognition and greater cognitive decline." (PMID 40312128, 2025). "We demonstrate that carrying two copies of APOE ε4 is associated with accelerated cognitive decline with aging." (PMID 39903109, 2025). "Previous research on the association between ApoE ε4 and cognitive decline after stroke is controversial." (PMID 40349252, 2025). "Extensive research has focused on the direct effect of APOE alleles on the risk for AD and cognitive decline." (PMID 41042284, 2025). "CMV seropositivity was linked to a faster rate of cognitive decline in statistical models that controlled for age, sex, education, race, vascular risk factors, vascular diseases and apolipoprotein E (APOE) ε4 genotype." (PMID 40597958, 2025). "Longitudinal studies have demonstrated the role of the APOE ε4 allele in accelerating cognitive decline in Aβ-positive individuals, particularly in memory and executive function." (PMID 40456910, 2025).